RIPK1 (receptor interacting serine/threonine kinase 1)
Diseases named in the same sentence as RIPK1 in open-access papers (continued):
Sharing a sentence is not in itself a finding about the gene and the disease.
acute kidney injury (10 papers, 2018 to 2025). Sudden and sustained deterioration of the kidney function characterized by decreased glomerular filtration rate, increased serum creatinine or oliguria. "We previously reported that wogonin administration in rodent models reduced RIPK1-mediated necroptosis following cisplatin-induced acute kidney injury; however, its underlying mechanism in the early stages of DKD needs to be evaluated." (PMID 34253875, 2022). "A novel small molecule Hsp90 inhibitor, C-316-1, attenuates acute kidney injury by suppressing RIPK1-mediated inflammation and necroptosis." (PMID 38704372, 2024). "Wogonin reportedly protected against cisplatin-induced acute kidney injury by targeting RIPK1-mediated necroptosis." (PMID 34253875, 2022). "RIPK1 KD mutants, RIPK3, and MLKL deficiency could alleviate acute kidney injury by decreasing necroptosis." (PMID 34977874, 2021). "The authors conclude that 3-MCPD can induce renal toxicity, inducing tubular cell death by activating the RIPK1/RIPK3/MLKL-related necroptosis pathway, generating acute kidney injury, and activating the programmed cell death pathway of tubular cells in kidney tissue." (PMID 40137488, 2025). "TWEAK/Tnfrsf12a axis has been shown to induce RIPK1-dependent necroptosis and acute kidney injury, suggesting that ALF might be also mediated by TWEAK/Tnfrsf12a axis and RIPK1-dependent necroptosis." (PMID 35853848, 2022). "Overall, our data reveal the relevance of RIPK3-pMLKL regulation for acute kidney injury and identifies an FDA-approved drug that may be useful for immediate clinical evaluation of inhibition of pro-death RIPK1/RIPK3 activities in human diseases." (PMID 29500402, 2018). "Among the investigated pathologies, necroptosis also demonstrates its implication in kidney diseases; indeed, both acute kidney injury (AKI) and chronic kidney disease (CKD) report increased levels of RIPK1, RIPK3, and MLKL, suggesting necroptosis as a crucial event in kidney injuries." (PMID 35682876, 2022).
cervical carcinoma (10 papers, 2014 to 2024). A carcinoma arising from either the exocervical squamous epithelium or the endocervical glandular epithelium. "In the present study, we found strong linkages between RIPK1 polymorphisms and cervical cancer susceptibility." (PMID 32272907, 2020). "In conclusion, our study reveals that RIPK1 polymorphisms alter the susceptibility to cervical cancer among the Uyghur population, and it suggests that RIPK1 polymorphisms exert significant roles in cervical cancer development." (PMID 32272907, 2020). "The associations between RIPK1 polymorphisms and cervical cancer risk were assessed under Binary logistic regression models." (PMID 32272907, 2020). "The objective of this study was to evaluate the relationship between RIPK1 polymorphisms and cervical cancer risk among the Uyghur population." (PMID 32272907, 2020). "We then performed stratification analysis on the association of RIPK1 polymorphisms with cervical cancer susceptibility." (PMID 32272907, 2020). "Furthermore, research has demonstrated that the low expression of RIPK3 and RIPK1, as observed through immunohistochemical staining, is associated with a worse prognosis in cervical cancer patients." (PMID 38338850, 2024). "Hence, we explored the association between RIPK1 polymorphisms and cervical cancer susceptibility stratified by age." (PMID 32272907, 2020). "Finally, although we identified the close associations between RIPK1 polymorphisms and cervical cancer risk, the underlying mechanism is still unclear." (PMID 32272907, 2020). "Specially, it was observed that age and stage of cervical cancer could affect the relationship between four RIPK1 polymorphisms and cervical cancer among the Uyghur population." (PMID 32272907, 2020). "Furthermore, we found the genetic variants in RIPK1 contribute to different clinical outcomes among cervical cancer patients, which suggests the necessity of the study on genetic susceptibility." (PMID 32272907, 2020). "Therefore, to further explore the role of RIPK1 polymorphisms in cervical cancer, we conducted a case-control study to assess the impact of RIPK1 polymorphisms in cervical cancer susceptibility among the Uyghur population in China." (PMID 32272907, 2020). "In our study, RIPK1 rs2077681was remarkablely related to cervical cancer risk after adjustment." (PMID 32272907, 2020). "Our findings demonstrated that RIPK1 polymorphisms were associated with cervical cancer susceptibility among the Uyghur population in China, and RIPK1 polymorphisms might be involved in the development of cervical cancer." (PMID 32272907, 2020). "Multivariate Cox regression analysis of cervical cancer patients (n = 250) and their clinical and pathological characteristics including nuclear RIPK1 expression regarding PFS." (PMID 37197430, 2023). "Multivariate Cox regression analysis was conducted to test for independent prognosticators for OS and PFS in the cohort of n = 250 cervical cancer patients and significantly showed that nuclear RIPK1 expression is an independent prognosticator for OS and PFS." (PMID 37197430, 2023). "First, we selected tumor (n = 50) and paracancerous (n = 20) tissues from patients with cervical cancer for IHC to clarify the function and clinical significance of RIPK1 in CC." (PMID 37516007, 2023). "Multivariate Cox regression analysis of cervical cancer patients (n = 250) and their clinical and pathological characteristics including nuclear RIPK1 expression regarding OS." (PMID 37197430, 2023). "Simultaneous expression of RIPK1 and RIPK3 in the nucleus is an independent positive prognosticator for OS and PFS further underlining a potential positive effect of necroptosis in cervical cancer patients." (PMID 37197430, 2023). "In cervical cancer patients, expression of nuclear RIPK1 is an independent positive prognosticator for OS and PFS." (PMID 37197430, 2023).
cervical carcinoma (continued). "They further demonstrated the depletion of UPS20 in HeLa cervical cancer cell lines, resulting in a reduced NF-κB-mediated pro-survival signal and increased receptor-interacting serine/threonine protein kinase 1 (RIPK1)-independent apoptosis." (PMID 35508480, 2022). "Significantly longer overall survival and progression-free survival rates could be detected in cervical cancer patients expressing nuclear RIPK1 or RIPK3 alone or simultaneously (RIPK1 and RIPK3)." (PMID 37197430, 2023). "Multivariate Cox regression analysis was conducted to test for independent prognosticators for OS and PFS in the cohort of n = 250 cervical cancer patients and significantly showed nuclear co-expression of RIPK1 and RIPK3 as independent prognosticators for OS and PFS." (PMID 37197430, 2023). "It suggests that age is not an important factor for the association of RIPK1 polymorphisms and cervical cancer." (PMID 32272907, 2020). "The expression or mutation of RIPK1 polymorphisms with aging would not be deleterious for cervical cancer." (PMID 32272907, 2020). "We did not observe significant associations between RIPK1 polymorphisms and risk of cervical cancer." (PMID 32272907, 2020). "Nonetheless, the role of RIPK1 polymorphisms has not been confirmed in cervical cancer." (PMID 32272907, 2020). "Our findings support this, showing a positive correlation between HSP90 expression and RIPK1 and RIPK3 in cervical cancer." (PMID 38338850, 2024). "Previous research, including our own, has shown that the expression of necroptosis-relevant proteins (RIPK1, RIPK3) correlates with a better OS and PFS in cervical cancer patients." (PMID 38338850, 2024). "In conclusion, RIPK1 and RIPK3 are independent positive predictors for overall survival and progression-free survival in cervical cancer patients." (PMID 37197430, 2023). "In conclusion, this study showed that RIPK1 and RIPK3 correlated with longer OS and PFS in cervical cancer patients and can therefore be described as positive prognosticators for cervical cancer." (PMID 37197430, 2023). "Aim of this study was the analysis of the expression of RIPK1, RIPK3 and pMLKL in cervical cancer tissue and the evaluation of its prognostic value on overall survival, progression-free survival and additional clinical parameters." (PMID 37197430, 2023). "The expression of RIPK1, RIPK3, and pMLKL in cervical cancer tissue microarrays of n = 250 patients was analyzed immunohistochemically." (PMID 37197430, 2023). "Spearman’s rank correlation coefficient was evaluated for RIPK1, RIPK3, pMLKL and various histopathological markers which were stained and analyzed in the applied cervical cancer patient collective of previous studies." (PMID 37197430, 2023). "Immunohistochemical staining showed that RIPK1 and pMLKL were expressed in the nucleus and cytoplasm while RIPK3 was expressed in the nucleus in cervical cancer tissue." (PMID 37197430, 2023). "In another multivariate Cox regression analysis, co-expression of nuclear RIPK1, nuclear RIPK3 and cytoplasmic pMLKL presented as a significant independent prognosticator for OS in cervical cancer patients." (PMID 37197430, 2023). "Aim of this study was to analyze the expression of RIPK1, RIPK3, and pMLKL in cervical carcinoma patient tissue and to correlate their expression with clinical parameters, overall survival (OS) and progression-free survival (PFS)." (PMID 37197430, 2023). "Necrosis of cervical cancer cells through phosphorylation of RIPK1, RIPK3, and MLKL, thereby triggering an antitumor immune response in cervical cancer." (PMID 36349142, 2022).
cervical carcinoma (continued). "RIPK1 rs6907943 and rs17548629 were protective factors for the higher-grade (III, IV) cervical cancer among the Uyghur population by stratification analysis." (PMID 32272907, 2020). "RIPK1 (receptor-interacting protein kinase-1) plays a role in cancer development, whereas no clear studies focused on the cervical cancer." (PMID 32272907, 2020). "Caspase8 could promote necroptosis by stabilizing RIPK1 and necroptosis was reported to be induced by RETrA (REactivation of Transcriptional Reporter Activity) through the phosphorylation of RIPK1 and RIPK3 thus playing a therapeutic role in cervical cancer." (PMID 36357839, 2022).
pancreatic ductal adenocarcinoma (10 papers, 2019 to 2025). An infiltrating adenocarcinoma that arises from the epithelial cells of the pancreas. "Moreover, upregulation of RIPK1 in tumor-associated macrophages (TAMs) contributes to immune tolerance and immunotherapeutic resistance in pancreatic ductal adenocarcinoma." (PMID 35957699, 2022). "In particular, the proteomics analysis derived from shows higher levels of RIPK1 compared to RIPK3 within the Pancreatic Ductal Adenocarcinoma in both normal and tumor tissues, which is also in line with our data (Fig. EV4A)." (PMID 40240880, 2025). "In pancreatic ductal carcinoma, there have been observations of elevated expressions of RIPK1 and RIPK3." (PMID 38546403, 2024). "It was found that in vivo experiments involving the deletion of RIPK3 or inhibition of RIPK1 resulted in a delay in the progression of pancreatic ductal carcinoma in mice." (PMID 38546403, 2024). "On the other hand, RIPK1/3- and MLKL-dependent necroptosis in pancreatic ductal adenocarcinoma (PDA) cells would recruit and activate immunosuppressive TAMs and myeloid cells." (PMID 35422482, 2022).
prostate carcinoma (10 papers, 2014 to 2024). A carcinoma that arises from epithelial cells of the prostate gland. "Therefore, some investigators have developed a novel bio-selenium nanoparticle in prostate cancer that can cause necroptosis by inducing TNF-α activation of RIPK1." (PMID 34869390, 2021). "Furthermore, P62-RIPK1-RIPK3-dependent necroptosis contributes to aging-related myocardial vulnerability to I/R injury and sorafenib induces DU145 prostate cancer cells death by exploring the association of P62 and RIPK1 via immunoprecipitation or a proximity ligation assay." (PMID 35165268, 2022). "A natural compound extracted from Ophiopogon japonicus named ophiopogonin D' (OPD') was proven to induce significant necroptosis by upregulating RIPK1 in prostate cancer cells." (PMID 37564206, 2023). "In conclusion, IDOAMP directly inhibited Aurora kinase A and promoted the RIPK1/RIPK3/MLKL necrosome activation to inhibit the prostate cancer." (PMID 35965682, 2022). "In summary, the results from our present study indicate that OPD′ has growth inhibitory effects on human prostate cancer cells and xenograft tumors, and these effects are at least partially mediated via its targeting of RIPK1." (PMID 29760660, 2018). "Sorafenib promoted the interaction of RIPK1 with p62 to induce necroptosis in DU145 prostate cancer cells." (PMID 29760660, 2018). "Furthermore, a rosin derivative known as IDOAMP was found to inhibit prostate cancer growth by activating the RIPK1/RIPK3/MLKL signaling pathway." (PMID 37564206, 2023). "In the Atg5-deficient prostate cancer cell line DU-145, sorafenib could mediate necroptosis by inducing the RIPK1/RIPK3/MLKL pathway, and this process can be blocked by the RIPK1 inhibitor Nec-1." (PMID 34869390, 2021). "Castration-resistant prostate cancer cells treated with metformin and simvastatin were shown to induce Ripk1- and Ripk3-dependent necrosis, suggesting that these necroptosis molecules may be important in the antitumor effects mediated by metformin." (PMID 29899823, 2018).
head and neck squamous cell carcinoma (9 papers, 2020 to 2025). A squamous cell carcinoma that arises from any of the following anatomic sites: lip and oral cavity, nasal cavity, paranasal sinuses, pharynx, larynx, and salivary glands. "In head and neck squamous cell carcinoma, RIPK1 downregulation increased the risk of metastasis through inhibition of NF-κB-pathway-dependent TLR3 receptor and by promoting apoptosis over necrosis." (PMID 40508046, 2025). "It was reported that RIPK1 expression was significantly downregulated in head and neck squamous cell carcinoma, and low expression in tumors was associated with progression of the disease." (PMID 32742497, 2020). "In head and neck squamous cell carcinoma (HNSCC) patients, the loss of RIPK1 and RIPK3 function caused by promoter hypermethylation is closely related with poor prognoses." (PMID 38799433, 2024). "Similarly, in metastatic head and neck squamous cell carcinoma, downregulation of RIPK1 is possibly mediated by enhanced methylation of the RIPK1 promoter in tumour cells and enhances protumorigenic properties such as cell migration." (PMID 41334873, 2025).
osteosarcoma (9 papers, 2016 to 2025). A usually aggressive malignant bone-forming mesenchymal neoplasm, predominantly affecting adolescents and young adults. "For example, the anticancer drug shikonin exerts an antitumor effect on osteosarcoma by triggering RIPK1- and RIPK3-dependent necroptosis." (PMID 40573272, 2025). "Shikonin significantly reduces osteosarcoma metastasis by inducing receptor-interacting protein 1 (RIPK1)- and RIPK3-dependent necroptosis." (PMID 37061535, 2023). "Shikonin exerts a dramatic anticancer effect on both primary and metastatic osteosarcoma by inducing RIPK-1 and 3- dependent necroptosis." (PMID 34680470, 2021). "The size of primary osteosarcoma tumors and lung metastases was significantly reduced by shikonin treatment accompanied the elevated levels for RIPK-1 and RIPK-3 proteins." (PMID 34680470, 2021). "The ability of necrostatin to protect sensitive osteosarcoma cells from death triggered by co-treatment with IAP antagonists plus TNFα imply that RIPK1 is an important determinant of sensitivity." (PMID 27129149, 2016). "Together these observations suggest that, for TNFα to kill osteosarcoma cells, RIPK1 is required and the activities of cIAP1 and XIAP must be diminished." (PMID 27129149, 2016). "To test the hypothesis that TNFRSF21 promoted necroptosis in osteosarcoma, we examined the phosphorylation levels of RIPK1, RIPK3 and MLKL." (PMID 38184626, 2024). "Consistent with this, the less sensitive osteosarcoma cell lines expressed lower levels of RIPK1." (PMID 27129149, 2016). "If the results of this study translate to human osteosarcomas, the levels of TNFα and RIPK1 in patients' tumors may predict their responses to treatment with pan-specific IAP antagonists." (PMID 27129149, 2016). "Mechanically, TNFRSF21 upregulated the phosphorylation levels of RIPK1, RIPK3 and MLKL to promote necroptosis in osteosarcoma." (PMID 38184626, 2024). "First, targeting RIPK1, a key factor of the secondary signaling complex formation, using shRNA, allowed us to overcome resistance in the in vivo K-HOS model of osteosarcoma." (PMID 36428719, 2022). "Necrostatin reduced or abolished the lethality triggered by treatment of osteosarcoma cells with IAP antagonists plus TNFα, implying that RIPK1 is required for this cell death." (PMID 27129149, 2016). "The K-HOS shRIPK1-1 cell line, which showed the highest inhibition of RIPK1 expression and a significant blockade of the TRAIL non-apoptotic pathways activation following AMG655 treatment, was selected for the induction of para-tibial orthotopic osteosarcoma in nude mice." (PMID 36428719, 2022).
asthma (8 papers, 2014 to 2025). "IRAK-1, IRAK-2, and RIPK1 were the only molecules, whose gene expression was associated to both farming environment and asthma." (PMID 24603716, 2014). "To assess whether epithelial RIPK1 deficiency affects the pathogenesis of asthma we analyzed the response of RIPK1AEC-KO and Ripk1fl/fl littermates to HDM-induced airway inflammation." (PMID 34045680, 2021). "Recently, it was shown that RIPK1 gene expression levels of white blood cells enhanced in farmers’ children compared to non-farmers’, and the farm-environmental mediated up-regulation in RIPK1 contributed partially to their reduced incidence of asthma." (PMID 37996860, 2023). "Collectively, these data suggest that Nec‐1 can antagonize TNF‐α‐induced necroptosis in 16HBE cells with MUC1 downregulation and thus, furtherly support that MUC1 as a novel protective molecule in cell necroptosis on asthma through mediating the p‐RIPK1‐s166 expression." (PMID 30666647, 2019). "Although we could show that the farm-environmental mediated up-regulation in IRAK-1, IRAK-2, and RIPK1 contributed partially to their reduced incidence of asthma." (PMID 24603716, 2014). "Inhibition of the RIPK1 and MLKL can ameliorate the severity of viral bronchiolitis in mice and prevent the later progression to asthma." (PMID 34977874, 2021). "Inhibition of the RIPK1 and MLKL could protect the mice from asthma." (PMID 34977874, 2021). "Lack of RIPK1 kinase activity or RIPK3 or MLKL deficiency did not protect mice with intact FADD signaling from HDM-induced airway inflammation, showing that RIPK1-RIPK3-MLKL-mediated necroptosis does not play an important role in HDM-induced asthma in wild type mice." (PMID 34045680, 2021). "HDM sensitization and challenge of RIPK1AEC-KO mice induced features of asthma pathology that were indistinguishable from the disease developing in their Ripk1fl/fl littermates, showing that AEC-specific deletion of RIPK1 did not considerably affect HDM-induced allergic airway inflammation." (PMID 34045680, 2021).